TOR2A (torsin family 2 member A)
Description:
Salusins -alpha and -beta may be endocrine and/or paracrine factors able to increase intracellular calcium concentrations and induce cell mitogenesis. Salusins may also be potent hypotensive peptides.
Synonyms: TORP1; FLJ14771
Tractability: Antibody: UniProt places it where antibodies can reach, with high confidence; its Gene Ontology location is reachable by antibodies, with high confidence; UniProt predicts a signal peptide or a membrane-spanning region. PROTAC: its protein half-life has been measured.
Gene: Protein-coding gene on chromosome 9 (127,731,516 to 127,735,355, reverse strand). Ensembl gene ENSG00000160404.
Subcellular location: Endoplasmic reticulum lumen; Secreted
Subcellular location (Human Protein Atlas): Endoplasmic reticulum; Plasma membrane; Predicted to be secreted
Gene Ontology:
Molecular function: identical protein binding; ATP binding; ATP hydrolysis activity
Cellular component: endoplasmic reticulum lumen; nuclear envelope; endoplasmic reticulum
Genetic constraint (gnomAD): Loss-of-function variants: 24 observed, 22.12 expected, observed/expected ratio (o/e) 1.09, 90% interval 0.79 to 1.52. The upper end of that interval is the gene's LOEUF score, 1.52, which puts it in group 6 of 6, group 1 being the genes least tolerant of losing a copy. Missense variants: 424 observed, 403.42 expected, observed/expected ratio (o/e) 1.05, 90% interval 0.97 to 1.14. Synonymous variants: 203 observed, 185.39 expected, observed/expected ratio (o/e) 1.1, 90% interval 0.98 to 1.23.
Homologues: Orthologues: chimpanzee TOR2A (99% identical), macaque TOR2A (97% identical), pig TOR2A (89% identical), dog TOR2A (89% identical), guinea pig TOR2A (88% identical), rat Tor2a (87% identical), mouse Tor2a (86% identical), rabbit TOR2A (64% identical), tropical clawed frog tor2a (56% identical), zebrafish tor2a (43% identical), Caenorhabditis elegans ooc-5 (36% identical), Caenorhabditis elegans tor-1 (35% identical), and 2 more. Paralogues in human: TOR1B (43% identical), TOR1A (41% identical), TOR3A (36% identical), TOR4A (23% identical).
Diseases named in the same sentence as TOR2A in open-access papers:
TOR2A is named in the same sentence as 19 diseases in open-access papers, as found by Europe PMC text mining. Sharing a sentence is not in itself a finding about the gene and the disease. The quoted sentences say what the papers report.
ovarian carcinoma (2 papers, 2022 to 2025). A malignant neoplasm originating from the surface ovarian epithelium. "Compared with other cancer cell lines, ovarian cancer cells displayed a notable dependency on TOR2A and integrin-linked kinase." (PMID 40953111, 2025). "In population-based studies, TPMT, TOR2A, KIF11, and EIF5A were reported to be associated with prognosis in other tumours, such as childhood acute lymphoblastic leukaemia, ovarian cancer, breast cancer, and colorectal cancer." (PMID 35421138, 2022).
blepharospasm (1 paper, 2019). "However, a follow-up study reported that all variants detected in GNAL, CIZ1, and TOR2A seemed to be benign in 132 blepharospasm patients." (PMID 32038460, 2019). "Interestingly, a recent study showed that deleterious variants in CACNA1A, REEP4, TOR2A, ATP2A3, HS1BP3, GNA14, and DNAH17 were involved in blepharospasm, and none of these variants except for CACNA1A has been reported to be associated with blepharospasm." (PMID 32038460, 2019).
Dystonia (1 paper, 2023). An abnormally increased muscular tone that causes fixed abnormal postures. "Mutations in TOR2A have been implicated in various dystonic phenotypes, including both isolated blepharospasm and more complex forms of dystonia." (PMID 38076033, 2023). "Other TOR2A variants have been reported in patients with dystonia." (PMID 38076033, 2023). "It is possible that TOR2A plays a larger role in generalized and other anatomical distributions of dystonia." (PMID 38076033, 2023). "The role of TOR2A in BSP and other forms of dystonia remains indeterminant." (PMID 38076033, 2023).
cancer (2 papers, 2018 to 2025). A tumor composed of atypical neoplastic, often pleomorphic cells that invade other tissues. "These CNV regions encode nineteen known genes, and some of which have been shown to affect aging-related phenotypes such as the shortening of telomere length (ZNF208), the risk of cancer (FOXA1, LAMA5, ZNF716), and vascular and immune-related diseases (ARHGEF10, TOR2A, SH2D3C)." (PMID 29883365, 2018).
cardiovascular diseases (1 paper, 2024). "Salusins, which are translated from the alternatively spliced mRNA of torsin family 2 member A (TOR2A), play a vital role in regulation of various cardiovascular diseases." (PMID 38336819, 2024).
TOR2A also shares sentences with these, for which no sentence is quoted: acute lymphoblastic leukaemia (1 paper); acute pancreatitis (1); atherosclerosis (1); breast carcinoma (1); cardiac hypertrophy (1); carotid atherosclerosis (1); colorectal cancer (1); infection (1); multiple sclerosis (1); placental insufficiency (1); pulmonary hypertensive (1); relapsing-remitting MS (1); ST Elevation Myocardial Infarction (1); tumours (1).